NR2C2AP (nuclear receptor 2C2 associated protein)
Description:
May act as a repressor of NR2C2-mediated transactivation by suppressing the binding between NR2C2/TR4 and the TR4-response element in target genes.
Synonyms: TRA16
Tractability: PROTAC: its protein half-life has been measured.
Gene: Protein-coding gene on chromosome 19 (19,201,409 to 19,203,729, reverse strand). Ensembl gene ENSG00000184162.
Subcellular location: Nucleus
Subcellular location (Human Protein Atlas): Nucleoplasm
Pathways (Reactome):
Gene expression (Transcription): Nuclear Receptor transcription pathway
Gene Ontology:
Molecular function: protein binding
Cellular component: nucleoplasm; nucleus
Genetic constraint (gnomAD): Loss-of-function variants: 13 observed, 20.3 expected, observed/expected ratio (o/e) 0.64, 90% interval 0.42 to 1.02. The upper end of that interval is the gene's LOEUF score, 1.02, which puts it in group 4 of 6, group 1 being the genes least tolerant of losing a copy. Missense variants: 181 observed, 181.2 expected, observed/expected ratio (o/e) 1, 90% interval 0.88 to 1.13. Synonymous variants: 81 observed, 68.29 expected, observed/expected ratio (o/e) 1.19, 90% interval 0.99 to 1.43.
Homologues: Orthologues: chimpanzee NR2C2AP (98% identical), macaque NR2C2AP (96% identical), dog NR2C2AP (92% identical), pig NR2C2AP (90% identical), mouse Nr2c2ap (83% identical), guinea pig NR2C2AP (82% identical), rat Nr2c2ap (81% identical), zebrafish nr2c2ap (62% identical), tropical clawed frog nr2c2ap (56% identical), Drosophila melanogaster CG34213 (41% identical).
Diseases named in the same sentence as NR2C2AP in open-access papers:
NR2C2AP is named in the same sentence as 25 diseases in open-access papers, as found by Europe PMC text mining. Sharing a sentence is not in itself a finding about the gene and the disease. The quoted sentences say what the papers report.
bipolar disorder (1 paper, 2022). A disorder of the brain that causes unusual shifts in mood, energy, activity levels and the ability to carry out day-to-day tasks. "In the Bipolar disorder dataset, four risk variants were found to overlap with hmsLRI-E which were connected to the NR2C2AP gene (two variants), the MPP2 gene (one variant), and the LMS12 gene (two variants)." (PMID 35887306, 2022).
cancer (3 papers, 2013 to 2025). A tumor composed of atypical neoplastic, often pleomorphic cells that invade other tissues. "NR2C2AP, which was highly expressed in NSCLC, also known as TRA16, could promote cancer cell growth by enhancing the ERβ signaling pathway and was associated with lymph node metastasis and poor OS." (PMID 35096017, 2021).
NR2C2AP also shares sentences with these, for which no sentence is quoted: lung carcinoma (2 papers); tumor (2); acute myeloid leukemia (1); adrenocortical carcinoma (1); benign lung tumors (1); cervical cancer (1); cervical squamous cell carcinoma (1); colon adenocarcinoma (1); colon cancer (1); diffuse large B-cell lymphoma (1); glioblastoma (1); glioma (1); liver cancer (1); lung (1); lung adenocarcinoma (1); lung squamous cell carcinoma (1); lymph node metastasis (1); melanoma (1); non-small cell lung carcinoma (1); pancreatic adenocarcinoma (1); rectum adenocarcinoma (1); testicular germ cell tumor (1); thymoma (1).